MMP9 (matrix metallopeptidase 9)
Diseases named in the same sentence as MMP9 in open-access papers (continued):
Sharing a sentence is not in itself a finding about the gene and the disease.
ischemic stroke (continued). "A recent study showed that higher MMP-9 levels in the serum of patients with acute ischemic stroke is correlated with the severity of clinical symptoms; Therefore, MMP-9 may serve as an important biomarker for ischemic stroke patent." (PMID 30131754, 2018). "Mmp9 has been reported to be detrimental in acute stroke by aggravating blood brain barrier (BBB) disruption, which could lead to intracranial hemorrhage of ischemic stroke." (PMID 26030758, 2015). "Therefore, MMP-9 might be one of the potential candidate genes for the link between T2DM and ischemic stroke." (PMID 26330106, 2015). "Our finding that tPA does not amplify MMP-2 and MMP-9 in ICH potentially suggests that this drug is not activated by a parenchymal (i.e. extra-arterial) clot formation in the same way as it is activated by an intraluminal thrombus in ischemic stroke." (PMID 23408937, 2013). "However, it is not known whether MMP-9 activation is involved in COX-2-mediated BBB disruption in ischemic stroke." (PMID 32973660, 2020). "During ischemic stroke in mice, MMP-2 and MMP-9 have different roles in BBB disruption where MMP-2 does not contribute to acute tissue damage as evidenced by the absence of neuroprotection of MMP-2 knockouts." (PMID 33487119, 2021). "In a mouse model of ischemic stroke, the nonselective NOS inhibitor N-omega-nitro-L-arginine (L-NA) decreased MMP-9 expression." (PMID 23158556, 2012). "In a recently study on ischemic stroke rats, we found that NBO treatment inhibited gp91phox (or Nox2) expression and MMP-9 induction and reduced BBB disruption." (PMID 22146586, 2011).
pancreatic cancer (244 papers, 2006 to 2025). "CCL21 regulates pancreatic cancer immunity possibly through governing the expression of a panel of tumor-associated genes, including MMP-9." (PMID 29687228, 2020). "By combination of results from expression, survival and correlation analysis demonstrated that MMP9/ITGB1-miR-29b-3p-HCP5 competing endogenous RNA (ceRNA) sub-network was linked to prognosis of pancreatic cancer." (PMID 31061236, 2019). "In conclusion, we demonstrated that MMP-9 and TN-C were overexpressed in pancreatic cancer and were associated with tumor progression and prognosis." (PMID 26652622, 2015). "Other evidence has shown that suppression of FOXM1 leads to a reduction in MMP-2 and MMP-9 expression levels in pancreatic cancer cells, which is associated with an overall decrease in cancer cell migration, invasion and angiogenesis." (PMID 23229761, 2013). "Matrix metalloproteinase (MMP)-2 and MMP-9 are presumed to be associated with the progression and invasion of various types of cancer cells and are highly expressed in pancreatic cancer." (PMID 23833675, 2013). "MMP-9 has also been implicated in the progression of pancreatic tumors and its expression is associated with pancreatic cancer and pancreatic tumor metastasis." (PMID 22952646, 2012). "The correlation between CCL21 and MMP-9 in PANC-1 cells may provide valuable insights into molecular mechanisms underlying the functions of CCL21 in pancreatic cancer." (PMID 29687228, 2020). "Our in vitro and in vivo findings that nicotine induced metalloproteinases 9 and 2 are in accord with analyses by PCR and immunohistochemistry that revealed increases in MMP-9 associated with induction of vascular endothelial growth factor in pancreatic cancer cells exposed in vitro to nicotine." (PMID 25260978, 2014). "While, two genes respectively encoding MMP-2 and MMP-9 were simultaneously abnormal up-regulated in pancreatic cancer tissue from diabetic mice of both STZ and db/db, that could act as potential therapeutic targets for significantly suppressing the malignant progression." (PMID 33251135, 2020). "PLGA–PEG polymer particles with outer long-chain PEG- and MMP-9-cleavable linkers created smaller PLGA–b-PEG nanoparticles for enhanced uptake by pancreatic cancer cells." (PMID 40284474, 2025). "In pancreatic cancer, the co-expression of the long isoform of TNC with membrane-associated annexin A2 (ANXA2) and the co-expression of TNC with MMP9 are significant indicators of poor patient prognosis." (PMID 40046232, 2025). "From published studies, it is known that enhanced MMP-9 expression in macrophages induces its migration during inflammatory injury, mesenchymal transition in pancreatic cancer or Wilms’ tumor metastasis." (PMID 40496854, 2025). "The mechanism is that salidroside inhibits the expression of HIF-1α, MMP2, and MMP9 in BxPC-3 cells, making it a potential adjuvant drug for the treatment of pancreatic cancer." (PMID 40563539, 2025). "It has also been demonstrated that PKD2 mediates cell invasion through the expression and secretion of MMP-1 in glioblastoma and MMP-7 and MMP-9 in pancreatic cancer." (PMID 39408603, 2024). "The heightened expression of dihydropyrimidine dehydrogenase (DPYD) in pancreatic cancer not only accelerates pyrimidine degradation but also stimulates cell proliferation and invasiveness, accompanied by the upregulation of MMP9 and MEP1A." (PMID 39158384, 2024). "EEF1A2 was reported to facilitate the migration, invasion, and metastasis of pancreatic cancer cells by activating Akt and upregulating MMP-9 expression." (PMID 38957390, 2024). "After treatment with bevacizumab (a VEGF inhibitor) and doxycycline (a drug that can effectively inhibit angiogenesis like an MMP-9 inhibitor) for 14 days, the tumor volume in pancreatic cancer mice significantly decreased." (PMID 39555072, 2024).
pancreatic cancer (continued). "In pancreatic cancer cell-derived exosomes, proteins CXCR4 (C-X-C motif chemokine receptor 4) and MMP-9 were found to enhance the metastatic capabilities of pancreatic cancer cells." (PMID 38200509, 2024). "GW501516 is reported to inhibit pancreatic cancer cell invasion through the suppression of MMP-9 expression." (PMID 38667323, 2024). "In pancreatic cancer, MMP9 secreted by macrophages can promote mesenchymal transition, thereby promoting tumor growth." (PMID 37715019, 2023). "When pancreatic cancer cells were treated with the MS extract, the expression of MMP9, β-catenin, and vimentin decreased in a concentration-dependent manner, and the phosphorylation of STAT3 also decreased." (PMID 37550432, 2023). "siRNA knockdown of eukaryotic translation elongation factor 1 α2 (eEF1A2), a protein translation factor overexpressed in cancer cells, suppresses the migration and invasion of pancreatic cancer cells by downregulating MMP-9 and inactivating AKT." (PMID 35326412, 2022). "Western blot analysis was used to evaluate NGF, BDNF, GDNF, and MMP-9 protein expression in pancreatic cancer cells." (PMID 35126957, 2022). "Our research has proved the role of Nodal in tumor invasion, metastasis, and neural invasion of pancreatic cancer, but the exact mechanism of Nodal affecting MMP9 and neurotrophic factors is still unclear." (PMID 35126957, 2022). "In our study, we found Nodal can affect the expression of MMP9 and promote the invasion and metastasis of pancreatic tumor cells." (PMID 35126957, 2022). "Different from previous studies, this study demonstrated for the first time that miR-490-5p mimic attenuated the levels of MMP2, MMP9, and N-cadherin and enhanced E-cadherin level in pancreatic cancer cells, which was reversed by MAGI2-AS3 overexpression." (PMID 35043728, 2022). "Other studies have shown that TQ can downregulate the expression of MMP-9 in pancreatic cancer cells." (PMID 36686732, 2022). "In conclusion, TQ can downregulate NF-κB and MMP-9 and their interaction to inhibit the metastasis of pancreatic cancer both in vitro and in vivo." (PMID 36686732, 2022). "In pancreatic cancer, galectin-1 promotes the secretion of matrix metalloproteinase (MMP9) and IDO, and high expression of MMP9 and IDO can result in NK cell dysfunction." (PMID 36428567, 2022). "EVs from solid tumours such as breast and pancreatic cancer have been previously shown to increase the secretion of several pro-inflammatory factors including MMP9 and IL-6 from THP-1 monocytic cells." (PMID 33984826, 2021). "Silencing SENP1 levels perturbed prostate and pancreas cancer cells’ ability to metastasize through the down-regulation of matrix metalloproteinase 9 (MMP9)." (PMID 33923236, 2021). "Recent reports have shown that FOXM1 contributes to pancreatic cancer invasion and progression by increasing the expression of MMP-9, MMP-2 and VEGF and downregulated FOXM1 expression results in the inhibition of pancreatic cancer cell growth and invasion." (PMID 33867818, 2021). "NTS stimulation increased the expression of MMP‐9 and other pro‐inflammatory cytokines and chemokines in pancreatic cancer cells." (PMID 33034134, 2021). "In this way, MMP-9-responsive nanovesicles were able to control tumor growth more effectively than MMP-9-free vesicles, suggesting that MMPs can be used as an inducible “trigger” to enhance drug accumulation in pancreatic tumors." (PMID 34809634, 2021). "Fis is able to dose-dependently inhibit MMP-9 protein and mRNA expression in a pancreatic cancer cell line (AsPC-1 cells)." (PMID 33498927, 2021). "OPN is induced in pancreatic cancer cells in vitro and in patients’ sera, while OPN inhibition decreases VEGF and MMP9 levels, which are involved in pancreatic tumor development and metastasis." (PMID 33670492, 2021).
pancreatic cancer (continued). "Modulation of the pre-metastatic niche microenvironment in pancreatic cancer has been linked to systemic production of factors, such as VEGF, PIFG, MMP9, and extracellular vesicles among others." (PMID 32355248, 2020). "Interfering of YTHDF2 upregulates the expression of MMP2 and MMP9 that possess the capability to promote cell adhesion, thus enhancing the invasion and adhesion of pancreatic cancer cells." (PMID 31959747, 2020). "Natural compounds, including silibinin and oxymatrine, have inhibitory effect on MMP-2 and MMP-9 via p38 inactivation in gastric and pancreatic cancer cells." (PMID 32349276, 2020). "A previous study reported that MMP2 and MMP9 were mainly secreted by pancreatic cancer cells to modulate the neural cancerous microenvironment." (PMID 32064233, 2020). "STAT3 leads to the expression of NGF, MMP2, and MMP9 in pancreatic cancer cells so that they can migrate and invade." (PMID 32555170, 2020). "In contrast to these studies, one group reported decreased invasion capacity of pancreatic cancer cells in vitro upon PPARβ/δ activation with GW501516 as well as downregulated prometastatic Matrix metalloproteinase-9 (MMP9) expression." (PMID 32375405, 2020). "Overexpression of miR-21 in pancreatic cancer cells is positively associated with the overexpression of invasion-related genes, including MMP-2, MMP-9 and vascular endothelial growth factor (VEGF)." (PMID 32489562, 2020). "It is well demonstrated that MMP-9 is overexpressed in the pancreatic tumor microenvironment while cathepsin B is up-regulated in the pancreatic tumor cells." (PMID 32850662, 2020). "Among these genes, our study further proved that the expression of both MMP-2 and MMP-9 was abnormally upregulated in pancreatic cancer tissue under diabetic conditions." (PMID 33251135, 2020). "Rg3 effectively inhibits the formation of pancreatic cancer vasculogenic mimicry by downregulating the expression of VE-cadherin, EphA2, MMP9, and MMP2." (PMID 32733585, 2020). "A more detailed study, which included in vivo and in vitro experiments related to pancreatic cancer, demonstrated that S1P activates pancreatic stellate cells to produce matrix metalloproteinase-9 (MMP-9) through an S1P2-, c-Abl-, and NF-κB-dependent pathway." (PMID 31807117, 2019). "Taken all the three levels into consideration, we constructed a novel mRNA-miRNA-lncRNA triple sub-network, MMP9/ITGB1-miR-29b-3p-HCP5, which is significantly associated with prognosis of pancreatic cancer." (PMID 31061236, 2019). "For example, RNF13 is an ER/Golgi membrane-associated E3, and overexpressed RNF13 increases the invasive potential and gelatinolytic activity of pancreatic cancer by increasing matrix metalloproteinase-9 (MMP9) activity." (PMID 30832692, 2019). "MIP-3α, through its receptor CCR6, induce expression of MMP9 in pancreatic cells and thereby increase pancreatic cancer cell invasion through collagen Type IV." (PMID 30925924, 2019). "We previously demonstrated that FUT175 suppresses the activity of MMP-9 in pancreatic cancer cells by regulating NF-κB." (PMID 30336548, 2018). "MIP-3α can bind to CCR6 on pancreatic cells to upregulate their MMP9 expression, which increases pancreatic cancer cells invasion in collagen IV." (PMID 30060755, 2018). "The predictive potential of THBS1 and MMP9 for the prognosis of pancreatic cancer has been reported in a few previous studies." (PMID 29515771, 2018). "The present study showed that TNC induced migration and invasion in pancreatic cancer cells and regulated a number of metastasis-associated proteins, including the EMT markers, MMP9 and Paxillin." (PMID 29088796, 2017).
pancreatic cancer (continued). "VEDT inhibited pluripotency transcription factors such as Nanog, Oct4, and Sox-2, Notch-1 receptor, metastasis marker MMP9 as well as Kras downstream signaling factors pAKT and pERK in pancreatic CSCs, indicating Kras signaling in pancreatic cancer stemness." (PMID 28404939, 2017). "Collectively, our study provides a novel regulatory pathway involving TM4SF1, DDR1, MMP2 and MMP9, which promotes the formation and function of invadopodia to support cell migration and invasion in pancreatic cancer." (PMID 28368050, 2017). "Co-expression of TNC and MMP9 or MMP2 was associated with a poorer prognosis and was found to be an independent predictor of survival for pancreatic cancer patients." (PMID 29088796, 2017). "MMP2, MMP9 are two important MMPs that play a vital role in pancreas development got differentially methylated in pancreatic cancer." (PMID 28423671, 2017). "Alpha-mangostin has been known to possess the antioxidant and antitumor property, probably via reduction of NF-κB, Stat3, and MMP9 expression and inhibits pancreatic tumor growth in vivo." (PMID 28537893, 2017). "It has been reported that coexpression of MMP9 and TNC is significantly associated with pancreatic cancer metastasis." (PMID 29088796, 2017). "VEDT depleted VEGF and MMP9 expression in pancreatic cancer L3.6pl and MiaPaCa-2 cells and in pancreatic tumor tissue (CD31) compared with vehicle control." (PMID 28404939, 2017). "MMP-9, one of the two type IV collagenases, essential in degrading extracellular matrix during invasion is reported to be overexpressed in pancreatic cancer." (PMID 28881737, 2017). "We aimed to use the presence of active MMP-9 in the tumor microenvironment to potentiate targeted delivery and infiltration of NPs into the tumor tissue of pancreatic cancer patients." (PMID 27993133, 2016). "It has been reported that VEGF and MMP-9 expression reduced in the stable MUC4 knockdown pancreatic cancer cell line." (PMID 27287498, 2016). "In this study, we demonstrate that LXA4 can effectively attenuate cell invasion and MMP-9/MMP-2 expression in pancreatic cancer by inhibition of intracellular ROS accumulation and ROS-induced ERK activation." (PMID 26649143, 2016). "The study of mouse model has confirmed that tumor cells in MMP-9+/+ mice produce bigger pancreatic tumors with high index of MVD." (PMID 27429508, 2016). "In pancreatic cancer, neutrophils residing within the tumors express MMP-9, which then liberates vascular endothelial growth factor (VEGF) and promotes angiogenesis." (PMID 27169366, 2016). "In invasive pancreatic cancer cell lines, MMP-9 activity was reduced with V-ATPase blockade where V-ATPase was localized on plasma membrane, but was least affected in cells which demonstrated little V-ATPase plasma membrane localization." (PMID 25686833, 2015). "In 103 pancreatic cancer specimens, 43 samples exhibited the co-expression and co-location of MMP-9 and TN-C." (PMID 26652622, 2015). "The expression of the matrix metalloproteinases (MMPs) MMP-2 and MMP-9 was increased in miR-221/222 mimic-transfected pancreatic cancer cells." (PMID 25883224, 2015). "We found that the expression of MMP-9 (stain ratio: 88 %) and TN-C (stain ratio: 74 %) was increased in most of pancreatic cancers compared with normal pancreatic samples (stain ratio: 0)." (PMID 26652622, 2015). "The co-expression of MMP-9 and TN-C was an independent predictor of survival for pancreatic cancer patients." (PMID 26652622, 2015). "Because MMP-2 and MMP-9 are important factors that influence cell invasion, we showed that pancreatic cancer cell invasion is dependent on miR-221/222 regulation." (PMID 25883224, 2015). "To determine the relationship between pancreatic cancer and the expression of MMP-9 and TN-C, we analyzed the expression levels of MMP-9 and TN-C in 103 pancreatic cancers and 6 normal pancreatic samples by immunohistochemistry." (PMID 26652622, 2015).